CNR1 (cannabinoid receptor 1)
Diseases named in the same sentence as CNR1 in open-access papers (continued):
Sharing a sentence is not in itself a finding about the gene and the disease.
fibromyalgia (7 papers, 2022 to 2025). A chronic disorder of unknown etiology characterized by pain, stiffness, and tenderness in the muscles of neck, shoulders, back, hips, arms, and legs. "This study aims to explore the role of cannabinoid receptor 1 (CB1) on transient receptor potential V1 (TRPV1) signaling pathways in a mouse model of fibromyalgia." (PMID 40430245, 2025). "The present study aimed to clarify the role of cannabinoid receptor 1 (CB1) signaling in a mouse fibromyalgia pain model." (PMID 39598297, 2024). "Other genes associated with fibromyalgia that regulate nociceptive and analgesic neuronal pathways are the TAAR1 receptor gene, the regulator of G protein signaling 4 gene (RGS4), the cannabinoid receptor 1 gene (CNR1), and the ionotropic glutamate receptor AMPA 4 gene (GRIA4)." (PMID 39062116, 2024).
irritable bowel syndrome (7 papers, 2022 to 2025). Irritable bowel syndrome (IBS) is a chronic functional condition of the lower gastrointestinal (GI) tract characterized by abdominal pain or discomfort and disordered bowel habit (diarrhea, constipation, or fluctuation between the two). "This network of ECS receptors controls gastric motility, and as such, it is now understood that variants in the genes encoding for CNR1 are implicated in diseases characterised by altered motility including irritable bowel syndrome (IBS), particularly diarrhoea-predominant." (PMID 37884682, 2024). "Finally, SNPs in the CNR1 have been shown to affect THC’s impact in patients with irritable bowel syndrome." (PMID 41024302, 2025).
pulmonary fibrosis (7 papers, 2020 to 2025). Chronic progressive interstitial lung disorder characterized by the replacement of the lung tissue by connective tissue, leading to progressive dyspnea, respiratory failure, or right heart failure. "Cannabinoid receptor 1 (CB1R) expressing alveolar macrophages promotes profibrotic activation of macrophages in pulmonary fibrosis." (PMID 40608428, 2025). "Overactivity of the endocannabinoid/cannabinoid receptor 1 (CB1R) system contributes to the development of multiple fibrosing interstitial lung diseases, such as IPF, Hermansky-Pudlak syndrome pulmonary fibrosis (HPSPF), and radiation-induced PF." (PMID 40608428, 2025).
triple-negative breast carcinoma (7 papers, 2019 to 2025). An invasive breast carcinoma which is negative for expression of estrogen receptor (ER), progesterone receptor (PR), and human epidermal growth factor receptor 2 (HER2). "In triple-negative breast cancer (TNBC), CNR1 regulates fatty acid metabolism by modulating the PI3K-AKT/MAPK signaling pathways, thereby affecting the sensitivity of cells toward ferroptosis." (PMID 40302936, 2025).
alcohol use disorder (6 papers, 2020 to 2025). "The analysis of the (AAT)n repeat number polymorphism in the CNR1 gene revealed that in the group of alcohol use disorder subjects, significantly fewer repeats were present when compared with the controls (12.04 vs. 12.40, Z = −2.080, p = 0.0380)." (PMID 38791212, 2024). "The study of the (AAT)n repeat number polymorphism in the CNR1 gene revealed that in the group of alcohol use disorder subjects, significantly fewer repeats were present when compared with controls (12.04 vs. 12.40, p = 0.0380)." (PMID 38791212, 2024). "This last observation is interesting as human ECR1 contains the rs9444584 polymorphism; part of a haplotype block that has been implicated in reduced CNR1 expression and increasing susceptibility to alcohol abuse." (PMID 31608546, 2020).
Cachexia (6 papers, 2016 to 2025). Severe weight loss, wasting of muscle, loss of appetite, and general debility related to a chronic disease. "Recent research has suggested that cannabinoid receptor 1 (CB1) can regulate muscle metabolism and lead to muscle breakdown in individuals with cachexia (Dalle, Hiroux, and Koppo 2024)." (PMID 39743857, 2025).
ovarian carcinoma (6 papers, 2020 to 2025). A malignant neoplasm originating from the surface ovarian epithelium. "In another instance, eRNA‐QTL rs62431527 in CNR1 eRNA (CNR1e) exhibited strong colocalization with ovarian cancer (PPH4 = 0.99), whereas there was no colocalization with the eQTL of CNR1 (PPH4 = 0.00)." (PMID 39950845, 2025).
anorexia nervosa (5 papers, 2008 to 2021). A disorder most often seen in adolescent females characterized by a refusal to maintain a minimally normal body weight, an intense fear of gaining weight, a disturbance in body image, and, in postmenarcheal females, the development of amenorrhea. "The aim of this study was to analyse whether nucleotide sequence variations in the CNR1, FAAH, NAAA and MGLL genes are associated with anorexia nervosa (AN)." (PMID 19014633, 2008).
dermatitis (5 papers, 2019 to 2025). An inflammatory process affecting the skin. "Cannabinoid receptor-1 (CB1R) agonists have been shown to directly downregulate activity of cultured RBL-2H3 mast cells and mast cell activity in oxazolone-dermatitis and topical THC has been shown to reduce symptoms of DNFB-dermatitis independent of CB1 and CB2 receptors." (PMID 31052404, 2019).
diabetic cardiomyopathy (5 papers, 2017 to 2025). Diabetic cardiomyopathy is a disorder of the heart muscle in people with diabetes. "This is noteworthy since studies suggest that CB1R (cnr1 in zebrafish) activation plays an important role in diabetic cardiomyopathy via facilitating ERK activation." (PMID 37174727, 2023).
lymphoma (5 papers, 2013 to 2023). A malignant (clonal) proliferation of B- lymphocytes or T- lymphocytes which involves the lymph nodes, bone marrow and/or extranodal sites. "Cnr1, encoding for a cannabinoid receptor, has been suggested to retain Mantle Cell Lymphomas in the B cells follicles." (PMID 36110848, 2022).
sleep disorder (5 papers, 2017 to 2025). A change from the patient's baseline sleeping pattern, in the hours slept and/or an alteration/dysfunction in the stages of sleep. "C carriers of CNR1 rs6454674 genotype were associated with one of the PSQI subscales (sleep disturbances) in both AUD and controls, and neuroticism mediated this relationship in controls." (PMID 34566715, 2021). "C carriers of CNR1 rs6454674 genotype reported greater neuroticism scores (a = 2.619), with greater neuroticism scores associated with greater sleep disturbances (b = 0.011)." (PMID 34566715, 2021). "In controls, neuroticism mediated the relationship between CNR1 polymorphism and sleep disturbances." (PMID 34566715, 2021). "In conclusion, we report associations between CNR1/FAAH polymorphisms and subjective/objective sleep quality in alcohol-associated sleep disturbances." (PMID 34566715, 2021).
type 1 diabetes (5 papers, 2017 to 2025). "CNR1 expression was upregulated in circulating CD4+ T cells from individuals at type 1 diabetes onset (6.9-fold higher vs healthy individuals) and in sorted islet beta cells from donors with type 1 diabetes (3.6-fold higher vs healthy counterparts)." (PMID 38864887, 2024).
adenomyosis (4 papers, 2019 to 2022). The growth of endometrial tissue inside the muscular wall of the uterine corpus. "In women with adenomyosis, cannabinoid receptor 1 expression is downregulated." (PMID 35566763, 2022).
cardiac hypertrophy (4 papers, 2018 to 2022). "JZL184 administration regresses cardiac hypertrophy and the expression of cardiac Cnr1 alterations of complete deletion (CD) mice." (PMID 36217821, 2022).
Hepatitis (4 papers, 2020 to 2024). Inflammation of the liver. "GO analysis based on differentially expressed genes revealed greater involvement of Cnr1 gene in liver inflammation and hepatitis." (PMID 33298885, 2020).
inflammatory bowel disease (4 papers, 2013 to 2022). A spectrum of small and large bowel inflammatory diseases of unknown etiology. "Indeed, a polymorphism of CB1-encoding Cnr1 gene was found to modulate the susceptibility to Crohn's disease and ulcerative colitis, and was associated with patients affected by inflammatory bowel disease." (PMID 23620805, 2013).
polycystic ovary syndrome (4 papers, 2014 to 2025). A disorder that manifests as multiple cysts on the ovaries. "There are data providing association between some of the CNR1 polymorphisms and abdominal obesity, metabolic syndrome, microvascular damage, polycystic ovary syndrome (PCOS), and nonalcoholic fatty liver disease." (PMID 27034934, 2016).
preeclampsia (4 papers, 2014 to 2023). Preeclampsia is a hypertensive disorder of pregnancy that is characterized by new-onset hypertension with proteinuria presenting after 20 weeks of gestation, and depending on mild or severe forms may initially present with severe headache, visual disturbances, and hyperreflexia. "Experimental studies are required to determine the causative role of increased placental expression of cannabinoid receptor 1 in preeclampsia." (PMID 25444073, 2014). "Among them, the CNR1 and GRIN2B genes, encoding cannabinoid receptor 1 and NMDA-type ionotropic glutamate receptor subunit 2B, respectively, have been associated with the risk of preeclampsia in case-control studies." (PMID 36768581, 2023).
rhabdomyosarcoma (4 papers, 2013 to 2025). A rare aggressive malignant mesenchymal neoplasm arising from skeletal muscle. "From the study, the use of Cnr1 antagonist or genetic deletion attenuates migration of alveolar rhabdomyosarcoma to the lungs." (PMID 32372224, 2020). "A G protein–coupled receptor (GPCR) Cnr1 has previously been shown to induce PAX3-FOXO1 expression to augment cell invasive capacity in alveolar rhabdomyosarcoma." (PMID 32372224, 2020).
AIDS (3 papers, 2012 to 2021). A syndrome resulting from the acquired deficiency of cellular immunity caused by the human immunodeficiency virus (HIV). "Marinol (dronabinol), a cannabinoid receptor 1(CB1) agonist, has been approved in the United States of America (USA) for the clinical treatment of nausea and vomiting, and anorexia caused by cytostasis or AIDS." (PMID 35126132, 2021).
heroin addiction (3 papers, 2018 to 2024). "In genetic studies, it has been shown that rs1049353 polymorphism of the cannabinoid receptor 1 (CNR1) gene affects addictive behaviors such as alcohol, marijuana, and heroin dependence." (PMID 30546300, 2018).
Hodgkins lymphoma (3 papers, 2013 to 2022). A heterogeneous group of malignant lymphoid neoplasms of B-cell origin characterized histologically by the presence of Hodgkin and Reed-Sternberg (HRS) cells in the vast majority of cases. "In Hodgkin lymphoma, abundant CB1R was found in CD30+ HRS cells of cHL, whereas the surrounding reactive, non-neoplastic cell infiltrate was largely CNR1-negative." (PMID 35008410, 2022).
age (2 papers, 2017 to 2023). A temporal measurement of the time period elapsed since an identifiable point in the life cycle of an organism. "The results indicated that genes related to cognitive development were expressed in different developmental stages in humans and mice (including Cnr1 an age-related cognitive impairment gene)." (PMID 38020907, 2023).
alcohol addicts (2 papers, 2011 to 2017). "Variation in CNR1 has been linked to polysubstance abuse and associated with increased activity in reward-processing areas of the brain in response to drug cues for both marijuana and alcohol addicts." (PMID 21714860, 2011).
Atrophy (2 papers, 2013 to 2022). Any weakening or degeneration, especially through lack of use. "Additionally, Cnr1–/– mice reported several signs of accelerated bodily ageing: they displayed atrophy in the subdermal fat and testis earlier than their wild-type siblings." (PMID 36613469, 2022). "The hypothesis that CNR1 (AAT)n influences the relationship between inflammation and neuronal atrophy in MS was first demonstrated by OCT evaluation." (PMID 24391723, 2013).
chronic hepatitis C (2 papers, 2010 to 2014). "In this study we demonstrate the presence of cannabinoid receptor 1 (CB1) in the livers of patients with chronic hepatitis C, a finding that has not been previously reported." (PMID 20862263, 2010).
ependymoma (2 papers, 2021 to 2022). A WHO grade II, slow growing tumor of children and young adults, usually located intraventricularly. "Given the expression of CNR1 in medulloblastoma and ependymoma samples and cell lines, along with other putative cannabinoid receptors, we investigated the effects of THC and CBD on the survival of these cells in vitro." (PMID 33477420, 2021).
Gilles de la Tourette Syndrome (2 papers, 2020 to 2025). "Genotypic and allelic association analysis of studied CNR1 variants with most common co-morbid disorders in patients with Gilles de la Tourette syndrome." (PMID 32194619, 2020).
mental disorder (2 papers, 2024). A disease that has its basis in the disruption of mental process. "Many CNR1 × environmental interactions have been described involving cannabis use, stressful life events and childhood adversity on SSD susceptibility, SSD brain-based phenotypes and other mental disorders." (PMID 39457583, 2024).
uveal melanoma (2 papers, 2015 to 2018). A melanoma derived from melanocytes of the uveal tract. "Since the G protein-coupled cannabinoid receptor 1 (CB1) is expressed in uveal melanoma cells, we determined if either this receptor or its coupled G-proteins affect interactions between TRPM8 and TRPV1 in UM cells." (PMID 30483120, 2018).
bladder diseases (1 paper, 2021). "Future studies are needed to reveal the action of selective cannabinoid receptor 2 agonists and/or peripherally restricted synthetic cannabinoid receptor 1 agonists on bladder sensory neurons in animal models of bladder diseases." (PMID 34290614, 2021).
Constipation (1 paper, 2023). Infrequent or difficult evacuation of feces. "The relative mRNA expression of the core targets (Alb and Pon1) from the PPI network and other constipation-related targets (Cnr1, Nos, Ache and Grp) were further analyzed by qPCR." (PMID 36902274, 2023).
Corneal opacity (1 paper, 2022). A reduction of corneal clarity. "Release of endocannabinoids such as 2-AG following injury-induced cannabinoid receptor 1 (CB1) activation downregulates TRPV1-mediated inflammation and corneal opacity." (PMID 36045746, 2022).
essential tremor (1 paper, 2021). A relatively common disorder characterized by a fairly specific pattern of tremors which are most prominent in the upper extremities and neck, inducing titubations of the head. "Furthermore, endocannabinoid binding to astrocytes’ cannabinoid receptor 1 (CB1) exerts anti-tremor effects in an essential tremor animal model." (PMID 34298921, 2021).
immune thrombocytopenia (1 paper, 2019). "We also recently established that CNR1 deletion is associated with chronic and IVIg-resistant immune thrombocytopenia, but not with the transient form of the disease." (PMID 31632391, 2019).
keloid (1 paper, 2022). An irregularly shaped, elevated mark on the skin caused by deposits of excessive amounts of collagen during wound healing. "One gene that was significantly decreased in fibroblasts from the keloids when compared to nonlesional normal fibroblasts is cannabinoid receptor 1 (CNR1)." (PMID 36483731, 2022).
leukocytosis (1 paper, 2014). "Low CNR1 mRNA expression correlated to lymphocytosis defined as lymphocyte count >5×109/L (p=0.016) and to leukocytosis (p=0.0018)." (PMID 25594062, 2014).
lupus nephritis (1 paper, 2019). Glomerulonephritis in the context of systemic lupus erythematosus. "In SLE, deletion of CNR1 is associated with a higher frequency of lupus nephritis." (PMID 31632391, 2019).
mesothelioma (1 paper, 2022). A usually malignant and aggressive neoplasm of the mesothelium which is often associated with exposure to asbestos. "In all three mesothelioma cell lines, both CBD and CBG robustly upregulated mRNA for the cannabinoid CB1 receptor (CNR1), G protein-coupled receptor 55 (GPR55) and the 5-HT1a receptor (HTR1A)." (PMID 35954477, 2022).
ocular tumor (1 paper, 2018). "Since functional CB1 expression has been described in ocular tumor cells and in healthy ocular cells, we determined if 3-T1AM interacts also with the cannabinoid receptor 1 CB1." (PMID 30483120, 2018).
relapsing-remitting MS (1 paper, 2013). "We have already reported that the long alleles of (AAT)n repeat polymorphism of CNR1 gene (>11 repeats) represent a genetic risk factor for disease progression in relapsing-remitting MS." (PMID 24391723, 2013). "Of note, PI (EDSS/disease duration) was higher in the long AAT group (0.53±0.45 versus 0.31±0.27; p<0.01), according to the previous reported association between (AAT)n repeat polymorphism of CNR1 gene and disease progression in relapsing-remitting MS patients." (PMID 24391723, 2013).
Tics (1 paper, 2020). Repeated, individually recognizable, intermittent movements or movement fragments that are almost always briefly suppressible and are usually associated with awareness of an urge to perform the movement. "C allele of rs2023239 polymorphism of the CNR1 gene was associated with the occurrence of tics." (PMID 32194619, 2020). "Cannabis-based medicines may alleviate GTS-associated tics and variants of CNR1 gene encoding central cannabinoid receptor (CB1) are believed to be a risk factor for the development of some neurodevelopmental diseases." (PMID 32194619, 2020). "In conclusion, the obtained results indicate that the C allele of the rs2023239 polymorphism of CNR1 gene is a risk factor of GTS in the Polish population, associated with the occurrence of tics, but not with the co-existing psychiatric symptoms." (PMID 32194619, 2020).